CCDC163 (CCDC163 homolog)
Synonyms: C1orf231; CCDC163P; LOC126661
Gene: Protein-coding gene on chromosome 1 (45,493,866 to 45,500,163, reverse strand). Ensembl gene ENSG00000280670.
Subcellular location: Membrane
Subcellular location (Human Protein Atlas): Cytosol
Gene Ontology:
Cellular component: membrane
Homologues: Orthologues: chimpanzee CCDC163 (97% identical).
Diseases named in the same sentence as CCDC163 in open-access papers:
CCDC163 is named in the same sentence as 4 diseases in open-access papers, as found by Europe PMC text mining. Sharing a sentence is not in itself a finding about the gene and the disease.
CCDC163 shares sentences with these, for which no sentence is quoted: cblC (2 papers); dementia (1); Lyme disease (1); tumor (1).